IQGAP2 (IQ motif containing GTPase activating protein 2)
Description:
Binds to activated CDC42 and RAC1 but does not seem to stimulate their GTPase activity. Associates with calmodulin.
Tractability: Small molecule: a structure with a bound ligand is known. Antibody: its Gene Ontology location is reachable by antibodies, with high confidence; the Human Protein Atlas places it where antibodies can reach. PROTAC: ubiquitination databases record sites on it; its protein half-life has been measured.
Gene: Protein-coding gene on chromosome 5 (76,403,285 to 76,708,132, forward strand). Ensembl gene ENSG00000145703.
Subcellular location (Human Protein Atlas): Plasma membrane; Vesicles
Pathways (Reactome):
Signal Transduction: CDC42 GTPase cycle; RAC1 GTPase cycle; RHO GTPases activate IQGAPs; RHOG GTPase cycle
Immune System: Neutrophil degranulation
Gene Ontology:
Molecular function: actin filament binding; Arp2/3 complex binding; calmodulin binding; phosphatidylinositol-3,4,5-trisphosphate binding; small GTPase binding; actin binding; GTPase activator activity; GTPase inhibitor activity
Biological process: Arp2/3 complex-mediated actin nucleation; regulation of actin cytoskeleton organization; thrombin-activated receptor signaling pathway; mitotic actomyosin contractile ring assembly actin filament organization; signal transduction
Cellular component: cell surface; cytoplasm; extracellular exosome; filopodium; lamellipodium; actin cytoskeleton; cell cortex; cytosol; plasma membrane; secretory granule membrane; cell leading edge; microtubule; microvillus; plasma membrane bounded cell projection
Genetic constraint (gnomAD): Loss-of-function variants: 89 observed, 105.48 expected, observed/expected ratio (o/e) 0.84, 90% interval 0.71 to 1.01. The upper end of that interval is the gene's LOEUF score, 1.01, which puts it in group 4 of 6, group 1 being the genes least tolerant of losing a copy. Missense variants: 1,047 observed, 1,216.4 expected, observed/expected ratio (o/e) 0.86, 90% interval 0.82 to 0.91. Synonymous variants: 438 observed, 449.84 expected, observed/expected ratio (o/e) 0.97, 90% interval 0.9 to 1.05.
Homologues: Orthologues: chimpanzee IQGAP2 (97% identical), macaque IQGAP2 (96% identical), dog IQGAP2 (91% identical), pig IQGAP2 (90% identical), guinea pig IQGAP2 (89% identical), mouse Iqgap2 (89% identical), rat Iqgap2 (89% identical), rabbit IQGAP2 (79% identical), tropical clawed frog iqgap2 (72% identical), Caenorhabditis elegans pes-7 (24% identical). Paralogues in human: IQGAP1 (62% identical), IQGAP3 (52% identical).
Diseases named in the same sentence as IQGAP2 in open-access papers:
IQGAP2 is named in the same sentence as 85 diseases in open-access papers, as found by Europe PMC text mining. Sharing a sentence is not in itself a finding about the gene and the disease. The quoted sentences say what the papers report.
hepatocellular carcinoma (18 papers, 2010 to 2023). A malignant tumor that arises from hepatocytes. "Loss or down-regulation of IQGAP2 has been found in hepatocellular carcinoma, prostate cancer, ovarian cancer and GC." (PMID 32183047, 2020). "While the roles and underlying mechanisms of IQGAP2 in hepatocellular carcinoma, prostate cancer and ovarian cancer have been demonstrated, the biological functions of IQGAP2 in GC are still elusive." (PMID 32183047, 2020). "For example, it was showed that IQGAP2 deficiency results in an 86% incidence of hepatocellular carcinoma in IQGAP2 knockout mouse model." (PMID 22539939, 2012). "We recently reported that IQGAP2 deficiency leads to the development of hepatocellular carcinoma (HCC) in mice." (PMID 20977743, 2010). "And most of them reported that the mRNA expression of IQGAP2 was negatively associated with a variety of cancers, including hepatocellular carcinoma, gastric cancer, bladder cancer, breast cancer, kidney cancer, lung cancer, and so on, indicating the potential of IQGAP2 being a tumor suppressor." (PMID 34276655, 2021). "IQGAP2 has been reported as a tumor suppressor in hepatocellular cancer, prostate cancer, and gastric cancer." (PMID 37543576, 2023). "IQGAP2 expression is reduced and plays a tumor suppressor role in most solid cancer types wherein reduced levels of IQGAP2 correlated with poor overall survival of patients (gastric cancer, prostate cancer, hepatocellular carcinoma, ovarian cancer)." (PMID 37587471, 2023). "The disruption of IQGAP2 in mice promoted the occurrence of hepatocellular carcinoma and was reversed by the deletion of both IQGAP1 and IQGAP2, indicating the opposite biological effects of the two isoforms." (PMID 36275458, 2022). "Of note, IQGAP2 deficiency results in hepatocellular carcinoma in mice, but IQGAP1 and IQGAP2 double disrupted mice have less hepatocellular carcinoma and normal survival." (PMID 34034707, 2021). "IQGAP2 has been shown to have an anti-proliferative effect in vitro in human prostate cancer and hepatocellular carcinoma cell lines." (PMID 26047140, 2015). "IQGAP2 expression is downregulated in more invasive and metastatic liver cancer cell lines as well as most human hepatocellular carcinoma tissue." (PMID 22539939, 2012). "Moreover IQGAP2 has been identified as a tumour suppressor gene in hepatocellular carcinoma, gastric and prostate cancers." (PMID 28650955, 2017). "IQGAP2 interacts with the cytoskeleton, cell adhesion molecules, and several signaling molecules to regulate cell morphology and has been suggested to be a tumour suppressor in hepatocellular carcinomas." (PMID 25222612, 2014). "In the case of IQGAP2 knockout mice, they develop age-dependent hepatocellular carcinoma (HCC) with increased IQGAP1 expression." (PMID 37892237, 2023). "Both the IQGAP2 mRNA and IQGAP2 protein levels are downregulated in human hepatocellular carcinoma (HCC)." (PMID 29596304, 2018). "Iqgap2 belongs to a family of scaffolding proteins, which mediate Rho GTPase and Ca2+/calmodulin signaling in regulating multiple cellular processes, such as cell adhesion, motility, and exocytosis; Iqgap2-null mice develop spontaneous hepatocellular carcinomas." (PMID 28468239, 2017). "Numerous researchers have observed that IQGAP2 and IQGAP3 play antagonistic roles in gastric cancer, colorectal cancer, hepatocellular carcinoma, prostate cancer, ovarian cancer, breast cancer, and malignant lymphoma." (PMID 36831467, 2023). "The tumor suppressor role of IQGAP2 was first mentioned in hepatocellular carcinoma (HCC)." (PMID 36831467, 2023). "Mice lacking both Iqgap1 and Iqgap2 display relative protection against hepatocellular carcinoma (HCC) and longer survival compared to Iqgap2-/- mice, implying that at least in the liver IQGAP1 antagonizes activity of IQGAP2." (PMID 26047140, 2015).
hepatocellular carcinoma (continued). "There is growing evidence that IQGAP2 is a novel tumor suppressor counteracting the effects of IQGAP1, an oncogene, in several cancers, especially in hepatocellular carcinoma (HCC)." (PMID 22973521, 2012). "A new hepatocellular carcinoma (HCC) mouse model lacking a novel putative tumor suppressor IQGAP2 has been generated by our laboratory." (PMID 23951254, 2013).
gastric cancer (12 papers, 2012 to 2023). A primary or metastatic malignant neoplasm involving the stomach. "Further analysis in gastric cancer revealed the underlying mechanism, whereby IQGAP2 interacted with SHIP2, and increased its phosphatase activity, deactivating Akt and decreasing EMT." (PMID 36831467, 2023). "Loss of IQGAP2 expression in gastric cancer promotes invasion and is associated with promoter methylation." (PMID 36275458, 2022). "IQGAP2 methylation is significantly associated with loss of the IQGAP2 expression in the primary gastric cancer tissues as well as gastric cancer cell lines, thereby leading to tumor invasion and a poor prognosis." (PMID 29073199, 2017). "As in gastric cancer, hypermethylation-mediated inactivation of IQGAP2 was discovered in serous and clear cell ovarian cancer samples, and it was associated with worse progression-free survival." (PMID 36831467, 2023). "On the other hand, some reports indicate that IQGAP2 can act as a tumor suppressor in gastric cancer." (PMID 36831467, 2023). "In an in vitro experiment, suppression of IQGAP2 increased cell invasion in gastric cancer cell lines, revealing its probable tumor suppressor role." (PMID 36831467, 2023). "IQGAP2 was found methylated and lost in gastric carcinoma tissues compared with gastric mucosa, and patients with IQGAP2 inactivation by methylation had a significantly worse prognosis." (PMID 36831467, 2023). "The upregulation of IQGAP2-induced apoptosis has also been observed in breast cancer and gastric cancer." (PMID 36362301, 2022). "IQ motif-containing GTPase activating protein 2 (IQGAP2) acts as a tumour suppressor in hepatocellular, prostate, and gastric cancers." (PMID 34034707, 2021). "In Oncomine database, IQGAP2 mRNA expression was found to be significantly decreased in different human gastric cancer subtypes, compared to normal tissues." (PMID 29073199, 2017). "In contrast to IQGAP3, IQGAP2 expression was low in colorectal (42/53) and stomach cancer (23/47) whereas the expression was high in prostate (28/32) and brain cancer (19/49) in tumor tissue compared to uninvolved tissue." (PMID 29073199, 2017). "The relation between IQGAP2 and cancer was first mentioned in gastric cancer." (PMID 36831467, 2023). "While major studies have focused on IQGAP1, indicating an oncogenic role in most cancers, IQGAP2 has received less attention and has been described as a tumor suppressor in most cancers, including gastric cancer, prostate cancer, ovarian cancer, and breast cancer." (PMID 36362301, 2022). "Additionally, IQGAP2 inactivation by hypermethylation is found in human gastric cancer samples and IQGAP2 knockdown with siRNA increased the invasive capacity of MKN45 gastric cancer cell line." (PMID 22539939, 2012). "The discovery of both genetic and epigenetic mechanisms for repressing IQGAP2 expression in gastric cancer provides strong evidence in support of IQGAP2 acting as a tumor suppressor gene and calls for further investigation on the role of IQGAP2 in gastric tumor development." (PMID 22539939, 2012). "IQGAP2 has been reported to promote the migration and invasion of HCC, prostate, ovary, and gastric cancer cells." (PMID 33846302, 2021). "The Kaplain-Meier analysis revealed significant correlation of IQGAP2 and IQGAP3 expression with the survival of the gastric cancer patients." (PMID 29073199, 2017). "A subsequent study demonstrated that IQGAP2 may regulate gastric cancer through the AKT pathway, which is highly activated in nearly 80% of gastric cancers." (PMID 36831467, 2023).
prostate carcinoma (12 papers, 2012 to 2023). A carcinoma that arises from epithelial cells of the prostate gland. "However, IQGAP2 overexpression is protective against tumorigenesis, as the loss or downregulation of IQGAP2 has been shown to play a role in development of hepatocellular, gastric, and prostate cancer." (PMID 25325012, 2014). "IQGAP2 inhibited cell proliferation and invasion of prostate cancer cell lines through enhancing E-cadherin promoter activity via inhibiting AKT activation." (PMID 36831467, 2023). "Survival analysis of the public database revealed that downregulation of IQGAP2 in prostate cancer is positively correlated with recurrence and metastasis." (PMID 36831467, 2023). "Analysis of the transcriptome revealed that IQGAP2 was overexpressed in prostate cancer tissues compared with normal adjacent prostate tissue." (PMID 36831467, 2023). "The gene IQGAP2 located on the same site was reported to be a tumor suppressor gene for prostate cancer." (PMID 36045445, 2022). "On the contrary, 87.5% of prostate cancer sample showed strong staining for IQGAP2 than 47.37% of BPH samples." (PMID 29073199, 2017). "Previous report for prostate cancer also reports showed just opposite IQGAP2 expression levels, warranting further study." (PMID 29073199, 2017). "Further molecular experiments confirmed the suppressor role of IQGAP2 in prostate cancer." (PMID 36831467, 2023). "The expression of IQGAP2 in prostate cancer is contradictory." (PMID 36831467, 2023). "Decreased expression of IQGAP2 in prostate cancer promotes cell proliferation by activating Akt." (PMID 36275458, 2022). "Indeed, other reports found that IQGAP2 was overexpressed in tissues of colon cancer and prostate cancer." (PMID 32183047, 2020). "Similarly, the expression levels of IQGAP2 in prostate cancer were found to be upregulated in Oncomine." (PMID 29073199, 2017). "In this regard, future studies with higher sample size might help in providing a better perspective on the role of IQGAP2 in prostate cancer." (PMID 29073199, 2017). "However, a recent study, albeit with limited number of prostate tumor samples, has reported reduction in IQGAP2 at both mRNA and protein level, in prostate cancer." (PMID 29073199, 2017). "Recently, the tumor suppressing repertoire of IQGAP2 has been expanded to include prostate cancer." (PMID 22973521, 2012). "It has been discovered that IQGAP2 increases E-cadherin expression and inhibits EMT via a reduction of Akt activation in prostate cancer." (PMID 36831467, 2023). "Ectopic overexpression of IQGAP2 reduced proliferation of both DU145 and PC3 prostate cancer cell lines, as well as invasiveness of DU145 cells." (PMID 22973521, 2012). "On the other hand, IQGAP2 copy number alteration was not significantly changed in cancers, except prostate cancer where reduction of copy number was observed in 4.2% cases." (PMID 29073199, 2017). "Moreover, IQGAP2 gene copy number was also altered in prostate cancer, which does not correlate with the observed high expression levels in our in-silico and in-vivo data." (PMID 29073199, 2017).
breast carcinoma (10 papers, 2017 to 2025). "Overall, our findings suggest that IQGAP2 is negatively associated with proliferative and metastatic abilities of breast cancer cells." (PMID 33846302, 2021). "Analysis showed that lower IQGAP2 expression in breast cancer was significantly associated with higher age, lymph node metastasis, lymphovascular invasion, and higher cancer stage, but not with tumor size." (PMID 33846302, 2021). "Here we report a reduced expression of IQGAP2, which was associated with lymph node positivity, lymphovascular invasion, and higher age in breast cancer patients." (PMID 33846302, 2021). "In breast cancer, the miR-10b-5p, which has been reported to be dysregulated and linked to prognosis, could negatively target IQGAP2." (PMID 36831467, 2023). "Additional research has demonstrated that the expression level of the IQGAP2 gene influences the incidence of breast cancer." (PMID 39682792, 2024). "In a recent study, the increased expression of IQGAP2 significantly decreased the amount of VEGF-A in breast cancer cells, and the consequent phosphorylation of VEGFR2 in endothelial cells, which resulted in the phosphorylation of AKT molecules." (PMID 36831467, 2023). "IQGAP2 is a tumor suppressor, as a decreased expression has been observed in human breast cancer and HCC." (PMID 35785216, 2022). "To summarize, we have established for the very first time the role of IQGAP2 as a tumor suppressor in breast cancer, which regulates MEK-ERK and p38 pathways to reduce the cancerous properties of cells." (PMID 33846302, 2021). "We carried out this study with the primary aim to establish the role and molecular mechanism of IQGAP2 in breast cancer progression and its relation with IQGAP1." (PMID 33846302, 2021). "To identify the expression level of IQGAP2 in breast cancer, we performed IHC in breast cancer patients." (PMID 33846302, 2021). "We found an inverse correlation of IQGAP2 expression levels with oncogenic properties of breast cancer cell lines in estrogen receptor (ER) independent manner." (PMID 33846302, 2021). "Suppression of IQGAP1-mediated ERK activation is a possible route via which IQGAP2 restricts oncogenic properties of breast cancer cells." (PMID 33846302, 2021). "To determine the correlation of molecular subtypes of breast cancer with IQGAP2 expression levels, we determined mRNA and protein expression levels in cells of different breast cancer molecular subtypes." (PMID 33846302, 2021). "The ratio of IQGAP2/IQGAP1 would be crucial in assigning the prognostic significance for breast cancer." (PMID 33846302, 2021). "In light of the crucial roles played by other members of the IQGAP family across breast cancers molecular subtypes, we decided to explore the role of IQGAP2 in breast cancer progression." (PMID 33846302, 2021). "We also found that the knockdown of IQGAP2 promoted migration and invasion ability of breast cancer cells which was also evident in E-cadherin downregulation, and N-cadherin, Snail, Twist upregulation." (PMID 33846302, 2021). "Our IHC data revealed that IQGAP2 protein levels are significantly reduced in a large proportion of breast cancer cases, suggesting it to be a tumor suppressor, which is consistent with our previous datamining-based findings." (PMID 33846302, 2021). "We observed a significant change in expression of IQGAP2 between stage I to II in breast cancer and liver cancer and, between stage II to III in breast, colorectal, prostate, liver and kidney cancer." (PMID 29073199, 2017). "However, the knockdown of IQGAP2 in breast cancer and bladder cancer elevated the phosphorylation of MEK1/2 and ERK1/2, which resulted in promoting EMT." (PMID 36831467, 2023). "Our findings with GST-Pull-down experiments show the presence of an IQGAP2-IQGAP1 complex in breast cancer cells, hinting at the possibility of masking the pro-oncogenic effects of IQGAP1 and subsequent reduction of the phospho-ERK levels in the cells, similar to the phenomenon observed in HCC21." (PMID 33846302, 2021).